INS (insulin)
Diseases named in the same sentence as INS in open-access papers (continued):
Sharing a sentence is not in itself a finding about the gene and the disease.
infection (continued). "It has previously been reported that mutants for daf-2 (insulin/IGF receptor) and age-1 (catalytic subunit of phosphatidylinositol 3-OH kinase) exhibit enhanced resistance to PA14 infection, similarly to inx-14 mutants described here." (PMID 37928537, 2023). "In addition, kidneys also showed up-regulated endocrine networks involved in estrogen, prolactin, and insulin signaling pathways and thyroid hormone synthesis, supporting the bi-directional crosstalk between endocrine and immune systems in response to pathogen infection." (PMID 35163263, 2022). "Herein, we showed that CVB3/28 infection and CVB-TD50 RNA forms’ transfection diminished the insulin secretion in response to high glucose concentration in INS-1-E1 cells." (PMID 36560784, 2022). "Recently, it was shown that mRNA expression of insulin and C-peptide concentrations, a cleavage product of insulin processing, were decreased during persistent CVB4-E2 infection of human primary pancreatic ductal cells." (PMID 36560784, 2022). "The omission of insulin was the leading precipitating factor for DKA (43%), followed by infection (12%)." (PMID 36505109, 2022). "Although the INS-15, INS-20-19, INS-21, and INS-23 genes all have high expression at 0–2 h of the in vitro infection, the patterns of the protein expression in C. parvum are different among them." (PMID 34093467, 2021). "At 48 h infection, GSIS analyses indicated that insulin secretion was reduced in ILDR2-knockdown cells at both high glucose and KCl stimulation levels." (PMID 33863978, 2021). "The patients' perception towards an insulin delivery device can have a notable impact on their glycemic control level; it was reported that pain and fear perception could limit patients' adherence and lead to poor infection technique, resulting in suboptimal delivery of the insulin dose." (PMID 33927957, 2021). "Upon infection with SARS‐CoV‐2, insulin resistance pathway as well as the expression of inflammatory cytokines and chemokines, such as Interleukins, CCL‐ and CXCL‐family, and CASPASE 3 increase in hPSC‐derived pancreatic endocrine cells." (PMID 34561952, 2021). "Here, we demonstrated that insulin reduced not only UPEC infection in bladder epithelial cells, but also inhibited the JAK/STAT transduction pathway during infection in a high-glucose environment." (PMID 34946023, 2021). "SV-HUC-1 cells pretreated with 20 and 40 μg/mL insulin showed significantly reduced UPEC infection rates and colonized numbers post-infection compared to the 15 mM glucose-treated group." (PMID 34946023, 2021). "In primary human neurons and microglia in vitro, insulin suppressed infection-induced inflammatory responses and HIV-1 growth in microglia, and prevented infection-induced neuronal death." (PMID 34795562, 2021). "Using a human pluripotent stem cell (hPSC)‐based model, following infection with SARS‐CoV‐2, the hPSC‐derived pancreatic endocrine cells showed a substantial proportion of spike protein‐positive SARS‐S+ INS+ and SARS‐S+ GCG+ cells." (PMID 34561952, 2021). "Therefore, we speculate that omission of disinfection during subcutaneous insulin injections does not cause infection." (PMID 33916158, 2021). "Insulin treatment also reduced HIV DNA in the brain, however, this was only achieved when treatment was initiated at earlier time points post infection (e.g. 23 days post infection)." (PMID 32650790, 2020). "By 72 h post-infection, cytotoxicity of insulin-positive cells doubled and INS transcripts decreased by >5 fold, yet total insulin levels were comparable between CVB4-infected and uninfected cells." (PMID 32093375, 2020). "Whereas PDX1 + NGN3 resulted in appearance of only somatostatin-positive cells, infection with all three PNM factors resulted in expression of somatostatin and insulin in mutually exclusive cells." (PMID 33111125, 2020).
infection (continued). "A complex interplay between fever, seizure, and infection as combined stressors, triggering a cumulative, synergic interaction between proinflammatory cytokines and stress-related hormones (interleukins, growth hormone, insulin, glucagon) could offer a potential explanation." (PMID 32120784, 2020). "The results showed that BMI, infection (as an admission diagnosis), ICU admission, nutritional therapy, and insulin use were significant predictors (P-values 0.025, 0.012, <0.001, 0.021, and 0.030, respectively)." (PMID 32133264, 2020). "We observed a decline in INS and other β-cell phenotype transcripts and decreases in insulin secretion following CVB4 infection of SC-β cells." (PMID 32093375, 2020). "Our studies in vivo showed that feeding Ae. albopictus mosquitoes with a much higher level of insulin (more than 5 μM) can induce the phosphorylation of ERK, and enhance the resistance to DENV2 at the earlier infection stage." (PMID 32866199, 2020). "Three days after infection, IRS-1 expression and insulin sensitivity were tested under both basal and IR states." (PMID 31723029, 2019). "In diabetic animals, the infection (DN315) doubled the IFN-γ levels, and treatment with multiple doses of insulin potentiated this effect (3.3-fold)." (PMID 30705678, 2018). "After multiple treatments with insulin, the levels of IL-1β, IL-6, and IFN-γ were increased in the PeLF of diabetic rats after infection with either strain, and CINC-2 levels were restored in N315-infected animals." (PMID 30705678, 2018). "To summarize the effects of miR-122 inhibition on lipid metabolism and insulin signaling, we showed that miR-122 inhibition leads to an increase in LPL, GLUT4 and FABPs at 4 days post-infection of miR-122 inhibitor." (PMID 30024933, 2018). "Insulin release was determined in INS-1E cells after short-term (8h, acute) infection and after long-term (72h, chronic) infection." (PMID 27631977, 2016). "Furthermore, we provide data suggesting that prostaglandin E2 (PGE2) production plays a key role in the reduction of insulin secretion after long-term infection and that insulin secretion by E. coli-infected ß-cells could be restored by using specific siRNAs against cPLA2 and iPLA2 isoforms." (PMID 27631977, 2016). "Infection of isolated human islets with either CVB3, CVB4, or CVB5 reduced their insulin content and glucose-stimulated insulin secretion." (PMID 26280364, 2015). "Moreover, the hypothesis that triethylamine disrupts endocrine signaling could also explain the negative effect that FlyNap has on mosquito survival during the first 24 h of infection, as insulin signaling and other endocrine factors modulate mosquito immune responses." (PMID 23875027, 2013). "Because of the widespread under-appreciation of the risks for bloodborne pathogen transmission when providing AMBG, CDC issued updated guidance on infection control practices during AMBG and insulin administration in 2011." (PMID 23300520, 2012). "In conclusion, our findings demonstrated that genetic manipulation producing infection by a combination of PDX-1 NeuroD1, and MafA and their subsequent expression significantly promoted insulin-producing function of mMSCs." (PMID 22761608, 2012). "Use of the C. elegans model has also delineated several conserved host pathways modulating infection outcomes, including the p38 mitogen-activated protein kinase (MAPK), TGF-β and DAF-2 insulin/IGF-1 signalling pathways." (PMID 22672310, 2012). "The principal findings of this study are that insulin rapidly stimulates l-arginine transport, an effect attenuated by the PI3 K inhibitor, wortmannin, or infection with adenoviruses expressing dominant-negative mutant Akt." (PMID 21871446, 2011). "As many as 50.0 and 23.0 integration events in average per cell were obtained following infection of WT HeLa P4 and LEDGF/p75-knockdown cells respectively by the ΔRev HIV-1 at a MOI of 10.0, in the presence of 100 μM INS." (PMID 20678206, 2010).
infection (continued). "The authors therefore concluded that intensive insulin therapy to maintain normoglycaemia in severely burned children could be safely and effectively implemented in a paediatric burns unit and that this therapy seemed to lower infection rates and improve survival." (PMID 20137090, 2010). "pylori infection influences the onset and progression of GLMD through multiple mechanisms, including the induction of inflammatory responses, exacerbation of oxidative stress, and impairment of insulin sensitivity." (PMID 41684649, 2026). "Most of the included studies reported that nonadherence to insulin treatment followed by infection was the most common triggering factor for the development of DKA." (PMID 40265138, 2025). "In our study, the leading trigger was insulin non-compliance, accounting for 50.5% of cases, followed by infections at 35%." (PMID 40755641, 2025). "Nonadherence to insulin treatment or antidiabetic medication and infection were identified as precipitating factors for developing DKA." (PMID 40265138, 2025). "We utilized a nonhuman primate model to compare the effects of infection with the SARS-CoV-2 delta variant in lean and obese/insulin-resistant adult male rhesus macaques over a 6-month time course." (PMID 40027795, 2025). "In many cases, these crises are precipitated by preventable factors such as missed insulin doses, intercurrent infections, or a lack of understanding about insulin adjustment during illness, especially in socioeconomically disadvantaged regions." (PMID 40755641, 2025). "Four of the studies included in this review reported a higher frequency of people live with DKA triggered by nonadherence to insulin treatment or antidiabetic medication, followed by infection." (PMID 40265138, 2025). "This case was characterized by very early onset after initiation of therapy, absence of infection or other common triggers, and resistance to standard treatment with insulin, glucose, and fluid resuscitation." (PMID 41127515, 2025). "The most common precipitant for the SGLT2i group was infection (60%), whilst insulin omission (53%) was the most common precipitant of the non-SGLT2i group, followed by infection (37%)." (PMID 40843859, 2025). "Four of these studies (80%) reported a higher frequency of DKA participants triggered by nonadherence to insulin treatment or antidiabetic medication, followed by infection, which makes nonadherence the most common triggering factor for the development of DKA." (PMID 40265138, 2025). "The reduced insulin sensitivity of skeletal muscle cells following infection, without changes in systemic glucose levels, is an example of such an escalated yet still limited metabolic change." (PMID 39107476, 2024). "It is likely that suppression of insulin secretion during WNV infection in human cell culture prevented activation of JAK/STAT innate antiviral immune pathways, leading to a weakened response to infection." (PMID 38921161, 2024). "Recent data indicate, however, that the physiological changes in metabolism as a result of infection with influenza A, cytomegalovirus (CMA), and herpes simplex may trigger permanent deregulation of blood glucose levels and systemic insulin sensitivity." (PMID 38787222, 2024). "albicans infection depended on p38 MAPK and insulin signals." (PMID 38841375, 2024). "Topical ocular insulin was well tolerated and no adverse events (including infection) were reported with the treatment." (PMID 38794241, 2024). "In the liver, transcriptomic differences between the families were associated mainly with cytoskeletal organization, cell cycle regulation, and metabolic processes, including insulin signalling and lipid metabolism, regardless of infection status." (PMID 39712009, 2024). "The upregulation of PTPs after infection may increase the dephosphorylation of IRS-1 and further reduce the effect of insulin signaling." (PMID 38441470, 2024).
infection (continued). "Notably, among these DEGs in the liver at 24 hpi, there was an intriguing increase in the expression of genes involved in insulin and insulin-like growth factor (IGF) signalling in the resistant family after infection." (PMID 39712009, 2024). "This suggests that insulin-mediated mTORC1 activation may also drive NET formation, influencing the clearance of infection." (PMID 36992811, 2023). "Acute infection of the islets might involve enhanced IFN-α and impaired glucose-induced insulin secretion." (PMID 36768699, 2023). "In conclusion, the Insulin signaling pathway and Myc are involved in the regrowth of purged enterocytes and ACS appears to promote the recovery of the steady-state expression of Myc mRNA that is strongly reduced early on during the infection." (PMID 37636057, 2023). "Median values (25%–75% quartiles) of insulin, liver and muscle glycogen in Sprague–Dawley rats co-infected with Plasmodium berghei ANKA (Pb) and Trichinella zimbabwensis (Tz) (Pb + Tz), Pb mono-infection and Tz mono-infection." (PMID 35923890, 2022). "Because we showed an impairment of insulin maturation in mice infected with CVB3/28 and CVB-TD RNA forms, we performed infection and transfection of the beta cell line of rodent INS-1, with the CVB3/28 strain at a MOI of 1 and with CVB-FL or CVB-TD synthetic RNA, respectively." (PMID 36560784, 2022). "Infection of b-cells by SARS-CoV-2 can lead to cell death and decrease in insulin release; excess inflammation may also increase insulin resistance in peripheral tissues." (PMID 36992740, 2022). "Together, these results show that CVB3/28 infection and the inoculation of CVB-TD RNA populations in mice decrease the insulin secretion, possibly by an impairment of proinsulin to insulin maturation, and induce the production of autoantibodies against islet cells during chronic infection." (PMID 36560784, 2022). "This is particularly important in that, in the current study, mosquitoes took bloodmeals from viremic animals rather than from an artificial feeder spiked with non-physiologic levels of insulin, potentially convoluting the infection outcomes." (PMID 35458395, 2022). "GO analysis showed that these downregulated proteins were mainly related to the insulin response involved in dryness symptoms and the Gram-negative bacterial defense response and proteoglycan binding involved in infection." (PMID 36091838, 2022). "By linear regression, cord blood IL-6 in those without suspected infection was significantly correlated with cord blood leptin (N=79, R=0.39, P<0.001) but not insulin (R=0.10, P=0.37)." (PMID 35197933, 2022). "Our participants actively avoided media, they prepared for possible negative consequences by keeping a stock of insulin and by strictly complying with advices on infection control measures." (PMID 35393314, 2022). "For example, long-lived mutants in the insulin/IGF-1 signaling pathway are resistant to heat, oxidative stress, heavy metals, protein misfolding, and pathogen infection." (PMID 35966651, 2022). "In agreement with this study, the amount of insulin secreted by β cell line INS-1 was not affected by persistent CV-B4 E2 infection in our system." (PMID 34067388, 2021). "After all, skin irritations should not be neglected as they can lead to a serious infection, and insulin requirements usually increase in connection with febrile illnesses and other serious acute illnesses." (PMID 34828602, 2021). "Insulin/insulin-like growth factor highly conserved in arthropods is involved in different immune pathways; insulin inhibits RNAi pathway but activates JAK/STAT pathway eliciting antiviral effects in mosquitoes following infection with WNV, DENV, and ZIKV." (PMID 34956136, 2021). "Serum insulin concentrations did not vary over the infection period (P = 0.58); nor were there differences between treatment groups (P = 0.47)." (PMID 34673945, 2021).
infection (continued). "There are recommendations that patients using SGLT2 inhibitors should be monitored for ketosis using available home testing kits in case of infections and should discontinue the medication in case of SARS-CoV-2 while the administration of insulin is considered the safest pharmacotherapy choice." (PMID 34702335, 2021). "In multiple animal models of infection, insulin treatment decreases systemic cytokines independent of glucose levels." (PMID 33992101, 2021). "Omitting skin disinfection before the insulin injection was not the factor that affects symptoms of injection site infection." (PMID 33916158, 2021). "During normal years when patients do not have any significant illness or infections (Multimedia Appendix 2), the insulin-to-carbohydrate ratio follows a similar trend in all the subjects, where the insulin-to-carbohydrate ratio lies between 0.05 and 0.2." (PMID 32784178, 2020). "AM were obtained from nondiabetic and diabetic mice and then infected in vitro with Pb18 yeast to evaluate their infection capacity in the presence or absence of insulin." (PMID 33312173, 2020). "Fifteen hours post-infection, immunofluorescence spectroscopy was used to identify cells expressing EMCV capsid protein (AF-488-conjugated secondary antibody, green) and cells expressing insulin (CY3-conjugated secondary antibody, red)." (PMID 33100269, 2020). "Surprisingly, they also discovered that anti-HHV8 antibodies could selectively induce a further increase in insulin and glucose uptake in the latent HHV8-infection." (PMID 32168836, 2020). "When we measured glucose and insulin changes in infected animals, we did not observe any changes in fasted blood glucose until animals were ten to twelve weeks post infection, by which time we did not detect any difference in systemic insulin levels." (PMID 31220189, 2019). "In addition, Ad-Smads2/3/4 infection significantly increased in vitro insulin-stimulated 2-deoxy-glucose uptake in WAT and muscle, whereas Ad-Smad7 infection had the opposite effect." (PMID 29700281, 2018). "After 3 days of infection, the first set of diabetic and non-diabetic rats received 4 and 1 IU, respectively, of neutral protamine Hagedorn insulin and were analyzed 8 h later." (PMID 30705678, 2018). "ATCC 25923 infection did not alter the corticosterone levels under diabetic conditions or after insulin treatments." (PMID 30705678, 2018). "Infection with Lenti-B40, a recombinant lentivirus encoding BHLHE40, raised the level of BHLHE40 mRNA in the absence of insulin and prevented the rapamycin-mediated reduction of BHLHE40 mRNA in the presence of insulin." (PMID 29952285, 2018). "Insulin treatment, while altering other parameters that would help in a more efficient containment of the infection, did not promote any changes on the studied cytokines." (PMID 30426021, 2018). "We hypothesize that the high susceptibility of dorsal-zone OSNs to damage is facilitated by a decrease in insulin/IGF1 signaling and high chance of infection." (PMID 30470811, 2018). "The second set of diabetic and non-diabetic rats received 4 and 1 IU, respectively, of insulin 2 h before intraperitoneal infection and a half dose of insulin at 5 p.m. for the next 2 days and were analyzed 16 h later." (PMID 30705678, 2018). "In the absence of insulin, infection with Lenti-B40 increased the BHLHE40 mRNA to levels similar to those seen after insulin treatment." (PMID 29952285, 2018). "In contrast, both in the presence and absence of infection, supplementation with Methionine increased lipid droplets in the gut without depleting lipids in the fat body or decreasing insulin signaling." (PMID 28586382, 2017). "An ideal CSII catheter would produce fast and consistent insulin PK for an extended period of time (4–14 days) with no occlusions, leaks, or infections." (PMID 28981324, 2017).